GPX4 (glutathione peroxidase 4)
Diseases named in the same sentence as GPX4 in open-access papers (continued):
Sharing a sentence is not in itself a finding about the gene and the disease.
pancreatic cancer (continued). "In addition to mtDNA, the release of nDNA to cytosol caused by nuclear cathepsin B (CTSB)-mediated genomic DNA damage activates STING1-dependent autophagy and subsequent glutathione peroxidase 4 (GPX4) degradation, leading to ferroptotic cell death in human pancreatic cancer cells." (PMID 34078874, 2021). "These analyses indicate that GPX4 may be a prognostic marker for pancreatic cancer patients." (PMID 34503532, 2021). "Notably, 8‐OHG released under GPX4 deficiency activates the STING (stimulator of IFN genes) pathway, driving aberrant expression of inflammatory mediators such as IL‐6 and NOS2 (nitric oxide synthase 2), providing new insights into pancreatic cancer inflammatory microenvironment formation." (PMID 40919133, 2025). "Circ_0005397 in pancreatic cancer, which activates PCBP2 expression through KAT6A-mediated H3K9 acetylation at the PCBP2 promoter, leading to enhanced GSH synthesis, GPX4 activation, and consequent chemoresistance." (PMID 40403492, 2025). "Screening to identify a drug that inhibits EMT of pancreatic cancer cells led to the selection of ML210, a GPX4 inhibitor." (PMID 39858464, 2025). "For example, the simultaneous upregulation of GPX4 and ACSL3 prevents lipid peroxidation and protects pancreatic cancer cells from ferroptosis both in vitro and in vivo, as shown through IL15RA-STAT3-GPX4/ACSL3 signaling." (PMID 41226317, 2025). "Integrating the results of PRNP silencing and pharmacological interventions, we conclude that PRNP exerts a critical ferroptosis-suppressing role in pancreatic cancer cells by positively regulating SLC7A11 and GPX4 protein expression." (PMID 41394830, 2025). "Thiostrepton, a natural cyclic oligopeptide, reduces the viability and clonogenicity of pancreatic cancer cell lines and induces ferroptosis via STAT3/GPX4 signaling." (PMID 38918369, 2024). "The simultaneous upregulation of GPX4 and ACSL3 prevents lipid peroxidation and ultimately protects pancreatic cancer cells from ferroptosis bothin vitro andin vivo." (PMID 39396119, 2024). "In our study, we first demonstrated a positive correlation between HMGA2 and GPX4, where HMGA2 overexpression increased GPX4 levels in pancreatic cancer cells, reducing lipid peroxidation under the ferroptosis inducer RSL3." (PMID 38493165, 2024). "In KP4 high-mesenchymal state pancreatic cancer cells, ZEB-1 knockdown prevented the cells from GPX4-inhibitor-induced cell death." (PMID 37046995, 2023). "By analysing the TCGA dataset of pancreatic cancer (TCGA PAAD), we found that autophagy biomarkers, such as LC3B-II, were correlated with ferroptosis biomarkers, such as GPX4." (PMID 36248959, 2022).
pancreatic cancer (continued). "In one study, erastin was used to treat the pancreatic cancer cell line PANC1, and western blot analysis showed that the protein levels of the key ferroptosis factors GPX4 and GSH were significantly decreased, but LONP1 expression was upregulated." (PMID 34503532, 2021). "In pancreatic cancer cells, study showed that HMGA2 could bind and promote cis-element modification in the promoter region of the GPX4 gene by enhancing enhancer activity through increased H3K4 methylation and H3K27 acetylation, thus promoting GPX4 expression." (PMID 41142608, 2025). "Besides regulating GPX4, SLC7A11, and AIFM2 expression, NFE2L2 upregulates microsomal glutathione S-transferase 1 (MGST1), aiding cellular detoxification in pancreatic cancer cells against ferroptotic activators." (PMID 38844964, 2024). "Consequently, targeting GPx4 and other GPX family members offers a promising therapeutic strategy to sensitize pancreatic cancer cells to ferroptosis, potentially overcoming resistance to current treatments and improving patient outcomes." (PMID 39594547, 2024). "Furthermore, in pancreatic cancer cells treated with both FAC and wogonin, a significant decrease in Nrf2 and GPX4 protein expression was observed compared to cells treated with FAC alone." (PMID 36909174, 2023). "By analyzing the Cancer Therapeutics Response Portal (CTRP) database, we found that the elevated gene expression of SLC3A2 was positively correlated with resistance to GPX4 inhibitors such as RSL3, ML162, and ML210, especially in RLS3-treated pancreatic cancer cell lines." (PMID 37479744, 2023). "Moreover, we detected AgNP-induced disturbance of antioxidant system (SOD1, SOD2, GPX-4, CAT, and SOD3) in pancreatic cancer cells." (PMID 30186549, 2018). "Although little is known about the role of GPX4 in pancreatic cancer, FSP1 or lack of OPA1 or autophagy dysfunction may suppress ferroptosis independently of GPX4, such that ML210 caused EMT suppression." (PMID 39858464, 2025). "Furthermore, we used small interfering RNA to silenceIL15 in activated PSCs and detected whether it affects the protein level of pancreatic cancer cells.IL15 silencing decreased IL15RA, p-STAT3, GPX4 and ACSL3 expression levels." (PMID 39396119, 2024). "Conversely, GPX4 expression is weaker in pancreatic cancer than in nontumor areas." (PMID 36576648, 2023).
melanoma (73 papers, 2020 to 2026). A malignant, usually aggressive tumor composed of atypical, neoplastic melanocytes. "Higher GPX4 expression was associated with improved clinical outcomes in melanoma trials involving immune checkpoint inhibitors." (PMID 41142608, 2025). "Evidence has shown that the absence of CDR1as is directly associated with the heightened metastatic potential of melanoma cells, while cells expressing higher levels of CDR1as demonstrate increased sensitivity to GPX4 inhibitors." (PMID 39430757, 2024). "We investigated the effects of HPF in three BRAF-mutated melanoma cell lines and observed a decrease in the expression level of glutathione peroxidase-4 (GPX-4)." (PMID 37507910, 2023). "It has been further demonstrated for different types of cancer, including melanoma, that persisting drug-resistant cells that exhibited a gene signature of mesenchymal-like state were more susceptible to inhibition of GPX4." (PMID 32340261, 2020). "For instance, the loss of GPX4, a key enzyme in ferroptosis, has been shown to promote an immune response against melanoma cells, indicating that ferroptosis may play a role in antitumor immunity." (PMID 39430757, 2024). "The combination of anticancer therapies with GPX4 inhibitors eliminated senescent tumour cells in models of melanoma, prostate and ovarian cancer." (PMID 42032311, 2026). "To explore the involvement of additional SLC superfamily proteins in ferroptosis regulation, we employed a CRISPR/Cas9-mediated knockout screening targeting human SLC genes in A375 melanoma cells, using the GPX4 inhibitor RSL3 to induce ferroptosis." (PMID 39881208, 2025). "Ferroptosis, characterized by lipid peroxidation, can overcome melanoma resistance by targeting the solute carrier family 7 member 11 (SLC7A11)/glutathione peroxidase 4 (GPX4) axis." (PMID 40497999, 2025). "While ferroptosis can limit tumor growth, melanoma cells frequently upregulate antioxidant defense mechanisms, such as glutathione peroxidase 4 (GPX4), to escape ferroptotic cell death." (PMID 40376583, 2025). "For instance, hyperforin treatment in melanoma cells harboring BRAFV600E mutation induces heme oxygenase-1 (HMOX1) expression, increases transferrin expression, and lowers glutathione peroxidase-4 to trigger iron-dependent lipid peroxidation and autophagy." (PMID 41009046, 2025). "The knockdown of Hmox1 reversed the effects of melanoma-derived conditioned medium (CM), including the reduction in Gpx4 levels and the degradation of Ftl1." (PMID 39814705, 2025). "6-MF targets PTBP1 to inhibit circPIAS1 biogenesis and reduce circPIAS1-108aa.6-MF inhibits PI3K-AKT pathway; combined with IFN-γ, it enhances STAT1 phosphorylation, inhibits SLC7A11/GPX4 pathway, promoting melanoma ferroptosis." (PMID 41347180, 2025). "Arginase 2 (Arg2) promoted GPX4 expression and inhibited lipid peroxidation, whereas sorafenib downregulated Arg2 expression to induce ferroptosis in melanoma." (PMID 40497999, 2025). "Osteocytes treated with melanoma CM also showed increased Hmox1 expression, but Gpx4 expression was upregulated in melanoma CM-treated MLO-Y4 cells." (PMID 39814705, 2025). "Taken together, these findings showed an upregulation of Hmox1, downregulation of Gpx4, and an induction of ferroptosis in osteocytes by melanoma cells." (PMID 39814705, 2025). "One key mechanism through which LPO exerts its cytotoxic effects in melanoma involves glutathione metabolism disruption and glutathione peroxidase 4 (GPX4) inhibition." (PMID 40427437, 2025). "Our Western blot analysis revealed a notable downregulation of GPX4 expression in melanoma cells subjected to HT+RT treatment." (PMID 40545912, 2025). "GPX4 neutralizes lipid peroxides, protecting melanoma cells from oxidative damage and promoting their survival within the lipid-rich tumor microenvironment." (PMID 40376583, 2025).
melanoma (continued). "When combined with IFN-γ, it significantly enhances STAT1 phosphorylation levels and inhibits the SLC7A11/GPX4 axis, thereby promoting ferroptosis in melanoma cells." (PMID 41347180, 2025). "The combination of 6-MF and immunotherapy reduced melanoma proliferative capacity, increased intracellular oxidative stress, and promoted, phosphorylation to inhibit the SLC7A11/GPX4 signaling pathway and promote ferroptosis in melanoma cells." (PMID 41347180, 2025). "Western blot results showed that silencing MCM4 led to reduced GPX4 expression in both human and murine melanoma cells." (PMID 39290263, 2024). "A significant decrease in GPX-4 and/or FTH-1 expression levels was noted in all three BRAF-mutated melanoma cell lines, with a particularly pronounced effect seen with cabotegravir treatment." (PMID 38338893, 2024). "Combining lorlatinib with GPX4 knockout, a regulator of ferroptosis, significantly suppresses melanoma growth in vivo." (PMID 38562143, 2024). "Sorafenib, known for inducing ferroptosis, reduces Arg2 expression, accompanied by decreased Akt phosphorylation and GPX4 levels in melanoma cells." (PMID 38562143, 2024). "In a B16 melanoma model and MC38 colon carcinoma model, intratumoral GPX4-deficient Tregs also experienced ferroptosis, which lowered tumor burdens." (PMID 39188677, 2024). "BRAF inhibitors such as vemurafenib, by modulating lipid metabolism and enhancing dependence on GPX4, offer novel insights into addressing drug resistance in targeted melanoma therapy." (PMID 39430757, 2024). "BSO reduces tumor burden in mice and improves the susceptibility of melanoma and neuroblastoma cells to chemotherapy by inhibiting glutathione synthesis rate-limiting enzyme (GCL), inactivating GPX4, and inducing cell death." (PMID 37598126, 2023). "Transfer of CAR-T cells overexpressing GPX4 (GPX4 OE) significantly suppressed the growth of murine melanoma and colon cancer." (PMID 37398660, 2023). "GPX4 dependency makes melanoma cells derived from drug-resistant patients reliant on transforming growth factor beta (TGF-β)." (PMID 37795022, 2023). "Vemurafenib, along with erastin or RSL3, also increased ferroptosis in resistance melanoma cells by targeting GPX4 and System Xc− transporter." (PMID 37996827, 2023). "Other compounds such as gallic acid and hyperforin, well-known antioxidants, have demonstrated the ability to inhibit cell viability and induce ferroptosis in melanoma cells by decreasing GPX4 activity." (PMID 37373523, 2023). "Persistent drug-resistant melanoma cells in a mesenchymal-like state have been shown to be highly vulnerable to GPX4 inhibition." (PMID 37795022, 2023). "Robust generation of mitochondrial superoxide and production of IL-1β induced by Treg-specific ablation of GPX4 help to potentiate antitumor immunity and repress tumor growth in melanoma." (PMID 36003368, 2022). "In the present study, we demonstrate that sorafenib treatment leads to the downregulation of Arg2 at the mRNA and protein expression levels, which suppresses ferroptosis by activating the Akt/GPX4 signaling pathway in mouse melanoma cells." (PMID 36604146, 2022). "We also show that Arg2 suppresses ferroptosis by activating the Akt/GPX4 signaling pathway, negatively regulating sorafenib-induced cell death in melanoma cells." (PMID 36604146, 2022). "We test the utility of our approach with a pan-cancer analysis of ML210, an inhibitor of GPX4, and a melanoma-focused analysis of inhibitors of BRAFV600." (PMID 35581546, 2022). "Ferroptosis, characterized by typical mitochondrial dysfunction, has been proven to be a hopeful choice for melanoma treatment via multifarious signaling pathways, such as the inhibition of selenoprotein glutathione peroxidase 4 (GPX4)." (PMID 35186949, 2021). "We demonstrated that the genetic knockdown of GPX4 reduced the metastatic capacity of 27HCR B16F10 melanoma cells, when compared to that of their wild-type counterparts." (PMID 34429409, 2021).
melanoma (continued). "Accordingly, these studies identified that drug tolerant melanoma cell populations were selectively dependent on GPX4 for survival compared to treatment naïve cells." (PMID 34830962, 2021). "In contrast to the results with SOD and Cat there was a trend towards inhibition of TPP derivative toxicity that became significant when melanoma cells overexpressing GPx4 were treated with 16-TPP, relative to 16-TPP alone." (PMID 33378390, 2020). "Remarkably, it has been shown that therapy resistant ZEB1high melanoma cells are metabolically dependent on the glutathione peroxidase 4 (GPX4)-driven lipid-peroxidase pathway." (PMID 32796736, 2020). "Palma and collaborators investigated FSP1 dependency in metastatic melanoma as a follow-up on previous findings from the same team demonstrating that melanoma cells disseminated through the lymphatic system are resistant to ferroptosis via GPX4-independent mechanisms." (PMID 41484055, 2026). "This suggests that therapies targeting GPX4 could be particularly effective in melanomas resistant to apoptosis-inducing therapies, such as BRAF and MEK inhibitors." (PMID 40427437, 2025). "Therefore, future study investigating the interplay between OZO-induced autophagy and GPX4 protein stability are essential to precisely delineate the molecular mechanisms driving ferroptosis in melanoma cells." (PMID 41030783, 2025). "Notably, pharmacologic inhibition of GPX4 or glutathione synthesis has been shown to restore ferroptosis sensitivity and resensitize melanoma cells to BRAF-targeted therapy." (PMID 40909289, 2025). "Indeed, persister cells from breast, melanoma, lung and ovarian cell lines have been shown to acquire a dependency on GPX4." (PMID 39681067, 2024). "Future studies are warranted to investigate whether EZH2 might regulate ferroptosis via the GPX4 pathway in mucosal melanoma, further broadening the therapeutic potential of targeting EZH2 in ferroptosis-related cancer treatments." (PMID 39518098, 2024). "In addition, ablation of GPX4 induces chemoresistant A375 melanoma cell death, which can be reversed by ferrostatin-1, a ferroptosis inhibitor." (PMID 37795022, 2023). "In the A375 melanoma xenograft model, the residual tumor from GPX4 wild-type tumors relapsed after treatment, while the GPX4-deficient tumor did not." (PMID 37046995, 2023). "GSH and redox homeostasis have been widely demonstrated to play a crucial role in therapy-resistance and it has been recently reported that compounds able to inhibit GSH peroxidase 4 (GPX4) induce ferroptosis in BRAFV600E mutant melanoma cells increasing the sensitivity to Vemurafenib." (PMID 37534247, 2023). "Notably, our previous study has shown that when BRAF-mutated melanoma cell lines are treated with low micromolar concentrations of HPF, among many other proteins, they experience a depletion of GPX-4." (PMID 37507910, 2023). "Treg-specific ablation of GPX4 induces robust generation of mitochondrial superoxide and production of IL-1β to facilitate Th17 responses, both of which potentiate antitumor immunity and repress tumor growth in melanoma." (PMID 36003368, 2022). "Considering the great resistance LS174T LDH-KO cells showed toward ferroptosis-induction either by GPX4 inhibition or cysteine starvation, we were curious to investigate if the “Warburg-null” melanoma cell line, we previously obtained, shows the same phenotype." (PMID 36552620, 2022). "In our study, it is important to note that sorafenib-induced ferroptosis, GPX4 decrease and lipid peroxidation were accompanied by downregulation of Arg2 expression and Akt phosphorylation in mouse melanoma cells, which can be prevented by overexpression of Arg2." (PMID 36604146, 2022). "As a result, Arg2 may reduce lipid peroxidation by activating the Akt-GPX4 signaling cascade, which in turn eventually leads to the suppression of ferroptosis in mouse melanoma B16F10 cells." (PMID 36604146, 2022).